CDK4 (cyclin dependent kinase 4)
Diseases named in the same sentence as CDK4 in open-access papers (continued):
Sharing a sentence is not in itself a finding about the gene and the disease.
breast cancer (continued). "Furthermore, circACTN4 overexpression might upregulate the expression of CCNE1 and CDK4 through increasing AcH4 levels of MYC target genes, thereby promoting cell cycle progression and tumorigenesis in breast cancer." (PMID 40612865, 2025). "Recent findings have highlighted the role of N6-methyladenosine (m6A) modification in ER+ breast cancer, particularly its capacity to regulate mRNA dynamics, such as the expression of CDK6, a critical mediator in cell cycle progression and a known target of CDK4/6 inhibitors." (PMID 40303916, 2025). "By this also, it can be inferred that in HR+HER2− breast cancer subjects, not yet well-defined immunological mechanisms may be responsible for low sensitivity to CDK4/6is." (PMID 40244377, 2025). "Clinical trials have shown the efficacy of adding CDK4/6 inhibitors to standard endocrine therapy in hormone receptor (HR)-positive, human epidermal growth factor receptor II (HER2)-negative high-risk early breast cancer." (PMID 40377782, 2025). "CDK4/6i may redefine treatment paradigms in HER2-positive breast cancer, offering a potential, non-chemotherapy option with durable benefit in select patient populations." (PMID 40940886, 2025). "Remarkable progress in the survival rates of HR‐positive and HER2‐positive breast cancers has been made possible by the development of cutting‐edge treatments, such as monoclonal antibodies targeting HER2, Antibody‐drug conjugates, and inhibitors of cyclin‐dependent kinase 4/6 (CDK4/6)." (PMID 41144937, 2025). "Another agent under investigation in a biomarker-unselected fashion is gedatolisib, evaluated in the VIKTORIA-01 phase III trial in combination with fulvestrant, with or without palbociclib, for HR+/HER2− advanced breast cancer previously treated with a CDK4/6 inhibitor." (PMID 41226406, 2025). "Three CDK4/6 inhibitors, palbociclib, ribociclib, and abemaciclib, have been approved for use in the US for patients with hormone receptor-positive (HR+), human epidermal growth factor receptor 2-negative (HER2-) breast cancer in combination with endocrine therapy." (PMID 40282469, 2025). "Here, we report the efficacy and safety of capivasertib–fulvestrant versus placebo–fulvestrant in a Chinese cohort of patients with HR-positive/HER2-negative advanced breast cancer whose disease progressed during or after aromatase inhibitor therapy and with or without a CDK4/6 inhibitor." (PMID 40346047, 2025). "In addition to HR+ breast cancer cells, abemaciclib treatment significantly increased lysosomal content and sensitivity to lysosomotropic agents in MDA-MB-231 cells, a TNBC cell line that is responsive to CDK4/6 inhibition." (PMID 39930269, 2025). "Indeed, our bioinformatic analyses of data obtained from human breast cancer patients treated with CDK4/6 inhibitors further indicated a negative effect of CDK4 activity on survival and resistance to the treatment." (PMID 39788939, 2025). "Therefore, CDK4/6i-trained M1 TAM supernatant therapy surmounts the immunosuppressive tumor microenvironment and induces a tumor response to low-dose PD-1 immune checkpoint blockade therapy in breast cancers." (PMID 41082324, 2025). "Further studies are essential to better understand how CDK4/6 inhibitors affect the tumor microenvironment and how they might most effectively be incorporated into tailored treatment strategies for managing early stage HR+/HER2− breast cancer." (PMID 38448600, 2024). "Real-world evidence has suggested that patients with hormone receptor-positive advanced breast cancer and gBRCAm may have inferior outcomes with CDK4/6 inhibition or endocrine therapy versus those without gBRCAm45–49." (PMID 39237557, 2024). "This study was a multicenter retrospective evaluation of the electronic health records of 212 patients with HR + /HER2− advanced breast cancer in Andalusia, 175 (82.5%) patients using CDK4/6 inhibitors and 37 (17.5%) patients using endocrine therapy without CDK4/6 inhibitors (control group)." (PMID 38831191, 2024).
breast cancer (continued). "However, although CDK4/6i analogs have made a significant therapeutic progress not only in the treatment of breast cancer, their clinical efficacy is still limited by drug resistance occurrence." (PMID 39456957, 2024). "For instance, palbociclib (a CDK4/6 inhibitor) in conjunction with letrozole (24.8 months) resulted in considerably longer progression-free survival than letrozole alone (14.5 months) in patients with previously untreated ER-positive, HER2-negative advanced breast cancer." (PMID 38605349, 2024). "Furthermore, the panel used in this study did not include the RB gene, which was thought to predict the efficacy of CDK4/6 inhibitors, or the ESR1 or PIK3CA genes, which were frequently observed in breast cancer and were considered involved in endocrine therapy resistance." (PMID 38539518, 2024). "Cyclin-dependent kinase 4/6 inhibitors (CDK4/6i) represent the gold standard of the hormone receptor positive human epidermal growth factor receptor 2 (HER-2) negative advanced breast cancer." (PMID 38912058, 2024). "Cyclin-dependent kinase 4/6 inhibitors (CDK4/6i) combined with endocrine treatment represent the standard of care for advanced hormone receptor (HR) positive human epidermal growth factor receptor 2 (HER2) negative breast cancer." (PMID 38912058, 2024). "Additionally, combinations of neratinib with multi-kinase inhibitors like dasatinib or with downstream signaling inhibitors, such as mTOR and CDK4/6 inhibitors, have demonstrated strong preclinical efficacy by suppressing key survival pathways in HER2-positive breast cancer models." (PMID 39684551, 2024). "With the increasing use of CDK4/6 inhibitors, more prospective studies are needed to confirm the effect of PR status and first-line POD24 on the prognosis of advanced ER-high HER2-negative breast cancer patients receiving CDK4/6 inhibitors combined with endocrine as first-line therapy." (PMID 39020297, 2024). "Our findings show that RET is overexpressed in ER+ metastatic breast cancer resistant to combined CDK4/6i and endocrine therapy, rendering RET inhibition a promising therapeutic approach for patients who experience disease progression on combined CDK4/6i and endocrine therapy." (PMID 39931212, 2024). "This is also supported by previous work with CDK inhibitors in lung or breast cancer cells, where cells with developed resistance to CDK inhibitors present a limited response to these compounds, with minimal inhibition of the cell cycle progression and elevated CDK4 or 6 expressions." (PMID 38674017, 2024). "The effectiveness of CDK4/6 inhibitors in HR + breast cancer has been validated in clinical trials regardless of whether patients develop resistance to endocrine therapy." (PMID 39161906, 2024). "Capivasertib–fulvestrant therapy resulted in significantly longer PFS than treatment with fulvestrant alone among patients with HR-positive advanced breast cancer whose disease had progressed during or after previous aromatase inhibitor therapy with or without a CDK4/6 inhibitor." (PMID 38869741, 2024). "Even though the advent of CDK4/6i has dramatically improved the outcomes of patients with HR+/HER2− advanced breast cancer, about 20% of patients do not benefit from this therapy and may require different approaches upfront." (PMID 38338777, 2024). "Based on current treatment standards, most patients would receive CDK4/6 inhibitors in a first- or second-line setting at our institution; nevertheless, our results confirm that there is a subgroup of patients with metastatic HR+/HER2− breast cancer who can achieve a durable response with ET alone." (PMID 38791907, 2024). "However, this was the first trial that had mature data on the use of a CDK4/6 inhibitor as part of adjuvant treatment for early breast cancer, paving the way for more studies in the non-metastatic setting." (PMID 38279242, 2024).
breast cancer (continued). "Thus, we speculated that Narciclasine and Bruceine D could inhibit MCF7 cell proliferation through targeting MELK, CDK4, and MYC to regulate cell cycle in breast cancer." (PMID 38215156, 2024). "The Food and Drug Administration (FDA) recently approved dual CDK4/6 inhibitors, palbociclib, ribociclib, and abemaciclib in combination with other agents for the treatment of hormone receptor positive (HR+) advanced or metastatic breast cancer (A/MBC), as well as other subtypes of breast cancer." (PMID 39567714, 2024). "Indeed, the first FDA approval for a CDK inhibitor was not until 2015, when the selective CDK4/6i palbociclib entered clinical practice as treatment for hormone receptor (HR)-positive breast cancer." (PMID 38047585, 2024). "Furthermore, LY3484356 has displayed additivity in combination with CDK4/6 inhibitors, mTOR inhibitors, and PIK3CA inhibitors in blocking cell proliferation, as well as tumor growth inhibition in xenograft and PDX models of breast cancer." (PMID 39767607, 2024). "The randomized phase III EMERALD trial enrolled patients with ER-positive, HER2-negative advanced breast cancer who had one or two lines of endocrine therapy, required pre-treatment with a cyclin-dependent kinase 4/6 inhibitor, and had one or no lines of chemotherapy." (PMID 38869741, 2024). "Notably, this represents a new PFS and ORR record for the combination of CDK4/6i and AI in the first-line treatment of advanced HR + /HER2- breast cancer, further solidifying its role as the first-line therapy for endocrine-sensitive patients with HR + /HER2- advanced breast cancer." (PMID 38409585, 2024). "Among them, ribociclib, a CDK4/6 inhibitor, in combination with endocrine therapy (ET), has been shown to improve progression-free survival and overall survival over single agent ET in patients with metastatic HR+/HER2− breast cancer, including Luminal B disease." (PMID 38448600, 2024). "A pooled analysis by the FDA showed that all clinicopathological subgroups of patients with HR-positive, HER2-negative advanced breast cancer benefited from CDK4/6 inhibitors when combined with CDK4/6 inhibitors as first-line therapy, regardless of PR expression." (PMID 39020297, 2024). "Additionally, the CDK4/6 inhibitor palbociclib, by downregulating MUC16 expression, exerts an inhibitory effect on the expression of key genes in the breast cancer cell cycle and suppresses ER(-) aggressive breast cancer cells." (PMID 38361923, 2024). "However, as initially observed in a subset of breast cancers and here in most insensitive MPM cell lines, 15% of MPM tumours were highly proliferative despite the lack of CDK4 phosphorylation and thus are expected to be intrinsically resistant to CDK4/6i." (PMID 36453028, 2024). "Treatment with cyclin-dependent kinase 4/6 inhibitor (CDK4/6i), has demonstrated significantly improved progression-free survival in patients with hormone receptor-positive, HER2-negative, advanced breast cancer, when used in combination with endocrine therapies." (PMID 37509319, 2023). "Poly (ADP-ribose) polymerase (PARP), cyclin-dependent kinase (CDK) 4 and 6 (CDK4/6), Ak strain transforming (AKT), and fibroblast growth factor receptor (FGFR) are well-established therapeutic targets that have been the main focus of drug development for the treatment of breast cancer." (PMID 37415164, 2023). "This trial is currently ongoing to investigate the effect of combined capivasertib and fulvestrant on overall survival (OS), but these encouraging findings will likely lead to FDA approval for ER+ advanced breast cancer patients who progressed on endocrine therapy with or without a CDK4/6 inhibitor." (PMID 36901954, 2023). "Thus, we selected PKI-587 (PKI, gedatolisib), a highly potent dual panPI3K/mTOR inhibitor which was granted fast FDA track designation and breakthrough therapy designation in 2022 for HR+/HER2− breast cancer that failed to respond to CDK4/6 therapy." (PMID 36675180, 2023).
breast cancer (continued). "However, the outcome of HER2-low breast cancer with CDK4/6 inhibitors is conflicting and not consistent in the available reports." (PMID 37664544, 2023). "In the last two decades, the advent of CDK4/6 inhibitors, immunotherapy, and antibody–drug conjugates (ADC) improved survival outcomes for advanced or metastatic breast cancers (BC)." (PMID 36826152, 2023). "All CDK4/6 inhibitors were approved for metastatic HR+/HER2−negative breast cancer." (PMID 37895811, 2023). "This double-blind, randomised, Phase II study was undertaken in female patients with hormone-receptor (HR)-positive/human epidermal growth factor 2 (HER2)-negative advanced breast cancer with non-visceral disease who had received prior endocrine therapy with or without CDK4/6 inhibitors." (PMID 37308971, 2023). "The combination of a cyclin-dependent kinase 4/6 inhibitor (CDK4/6i) and endocrine therapy (ET) has become the new standard of care for patients with hormone receptor–positive, human epidermal growth factor receptor-2–negative (HR + /HER2 −) advanced breast cancer (ABC)." (PMID 37580773, 2023). "Additionally, among all 288 breast cancer patients treated at our center with or without additional irradiation, 117 required CDK4/6i dose reduction (41%)." (PMID 36765648, 2023). "For example, patients with HR+/HER2- advanced breast cancer and a high score in the ctDNA-based RB-LOH signature could be randomized to a chemotherapy-based treatment strategy versus the standard-of-care of endocrine therapy and CDK4/6 inhibition." (PMID 36859416, 2023). "Two hundred eighty-eight patients with ER positive HER2 negative advanced breast cancer were treated with CDK4/6 inhibitors in our center from November 2017 to February 2022 (149 pts with ribociclib, 117 with palbociclib, and 22 with abemaciclib; 285 women and three men)." (PMID 36765648, 2023). "ER+ breast cancer (ER+ BC) cells have shown an adaptive resistance to palbociclib‐induced cell cycle arrest by activating alternative signal pathway, independent of the CDK4/6‐RB signal transduction." (PMID 36127291, 2023). "Moreover, like most profile A cases in breast cancers and mesotheliomas, the ATC and PDTC cases lacking CDK4 phosphorylation were associated with over-expression of p16 mRNA and protein." (PMID 37964967, 2023). "The approval of cyclin-dependent kinase 4 and 6 inhibitors (CDK4/6i) in combination with endocrine therapy (ET) has remarkably improved the survival outcomes of patients with advanced hormone receptor-positive (HR+) breast cancer (BC), becoming the new standard of care treatment in these patients." (PMID 37835528, 2023). "Thus, circ_6014 could influence breast cancer cellular proliferation via regulation of the cell cycle through changes in CDK2/CCNE1 and CDK4/6/CCND1 cell cycle proteins and regulation of the G0/G1 phase of the cell cycle." (PMID 35383130, 2022). "Additionally, we show in breast cancer cells that abemaciclib stabilizes primed CDK4-cyclin D complex and displaces p21, not observed in CDK6-cyclin D models, resulting in altered sensitivity in breast cancer models with greater CDK6 expression." (PMID 36446794, 2022). "Interestingly, the addition of various inhibitors of autophagy (e.g., hydroxychloroquine) does not kill CDK4/6 inhibitor-treated breast cancer cells, but rather further enhances the senescent phenotype." (PMID 35248122, 2022). "Furthermore, a higher CCND1 amplification rate was also detected in TPBC compared with HR-negative, HER2-positive breast cancer, and more than 80% of TPBC were characterized by luminal A/B intrinsic subtype, indicating the sensitivity of TPBC to CDK4/6 inhibitor and endocrine therapy." (PMID 36396665, 2022). "Additionally, HSP suppressed aromatase enzyme activity, cyclin D1, CDK4, Bcl-xL, pS2 and induces CCAAT/C/EBP, pERK-1&-2, p57Kip2 expression, which contributes to reducing the tumour growth in MCF-7 breast cancer cells and female athymic mice model both in vivo and in vitro." (PMID 35128104, 2022).
breast cancer (continued). "Notably, there are currently no predictive factors of response to CDK4/6 inhibitors, and ER positivity is deemed to be the only robust marker in predicting CDK4/6 response in breast cancer patients." (PMID 36135204, 2022). "Thus, we selected MCF-7 and T47D cells, both of which were ER+HER2− breast cancer cells, to further explore whether S6K1 amplification confers resistance to CDK4/6 inhibitors in vitro." (PMID 36042494, 2022). "In particular, glioblastoma, breast cancer, colon cancer, melanoma, lung adenocarcinoma, head and neck cancer, pancreatic cancer, liver cancer, and prostate cancer cohorts showed the most significantly (p < 0.001) elevated CDK2, CDK4, CDK6, and STAT3 expressions." (PMID 33668805, 2021). "Correlation analyses also indicated that CDK4 expression was positively correlated with expressions of CDK2 and CDK6 in liver cancer, lung cancer, prostate cancer, pancreatic cancer, melanoma, head and neck cancer, glioblastoma, breast cancer, and cervical cancer cohorts (r = 0.06~0.69)." (PMID 33668805, 2021). "Therefore, CDK4/6 inhibitors induce DUB3 inactivation, promote Snail1 protein instability, and reduce cell migration, thus inhibiting metastasis in xenograft models of breast cancer." (PMID 34454495, 2021). "About 20% of breast cancer patients treated with CDK4/6 inhibitors never respond to treatment." (PMID 34830174, 2021). "Disorders in cell-cycle-related pathways have key influences on breast cancer prognosis, and our feature selection result highlights that CDK1, CDK4, AURKA, and PLK1 may play vital roles in the complex cell cycle regulatory network, which in turn affects breast cancer prognosis." (PMID 34290286, 2021). "In this study, we show that standard combined CDK4/6i and endocrine therapy does not efficiently suppress the growth of ER+ breast cancer cell lines and tumor xenografts resistant to fulvestrant, while the addition of AKTi results in profound growth inhibition." (PMID 34433817, 2021). "In this study, we used endocrine sensitive and resistant breast cancer cell line pairs to evaluate whether the WEE1 inhibitor, AZD1775, as a single agent or in combination with antiestrogens or CDK4/6 inhibitors, is a reasonable therapy option for inhibiting growth of resistant cells." (PMID 34277427, 2021). "Herein, we assessed the efficacy of the AKTi capivasertib, CDK4/6i palbociclib, and the ER degrader fulvestrant as single agents and in double and triple combinations in ER+MCF-7, T47D, and ZR-75-1 fulvestrant-resistant and fulvestrant-sensitive breast cancer cell models." (PMID 34433817, 2021). "Moreover, combined CDK4/6i and endocrine therapy is currently being tested in the adjuvant setting (NCT02513394, NCT03155997 and NCT03701334) and is expected to also be approved for treatment of primary ER+ breast cancer." (PMID 33398005, 2021). "Similarly, Watt and colleagues observed that breast cancer cell lines and PDX models treated with the CDK4/6i abemaciclib or palbociclib, displayed a remodeling of the chromatin architecture with a wide activation of transcription enhancers and super-enhancers." (PMID 34204543, 2021). "Moreover, current subtyping methods for ER+ breast cancers have not identified differential sensitivity to CDK4/6 inhibitors." (PMID 34642313, 2021). "However, recent substantial advances have been made in the management of HR+/HER2‒ advanced breast cancer (ABC) with the advent of targeted therapies, such as cyclin-dependent kinase 4/6 (CDK4/6) inhibitors, resulting in significant improvements in survival outcomes versus endocrine therapy alone." (PMID 34698970, 2021). "However, a preclinical study showed that treatment of CDK4/6i and ET-resistant ER+/HER2− breast cancer models with everolimus restored sensitivity to CDK4/6i, suggesting that combining these therapies may be an option after progression on CDK4/6i71." (PMID 34771560, 2021).